CXCL10 (C-X-C motif chemokine ligand 10)
Diseases named in the same sentence as CXCL10 in open-access papers (continued):
Sharing a sentence is not in itself a finding about the gene and the disease.
tumor (continued). "Consistent with their M1 differentiation, the macrophages upregulated expression of the chemotactic factors Ccl5 and Cxcl10, responsible for recruiting T lymphocytes (in this instance CAR T cells) into the tumor stroma." (PMID 37660083, 2023). "Studies have shown that CXCL9 and CXCL10 can directly recruit CD4+ and CD8+ T cells, and NK cells to the tumor site in various cancers." (PMID 38104126, 2023). "Research has shown that chemokine ligands CXCL10 and CXCL11 have anti-angiogenic properties and can effectively inhibit tumor progression." (PMID 36969851, 2023). "Previous studies have shown that PD-1 blockade treatment can enhance the T-cell-mediated anti-tumor response and also increase the levels of IFN-γ and CXCL10 in the TME." (PMID 36900218, 2023). "It has been demonstrated that M1 macrophages expressed high levels of CD86, MHC II and B7 and mediated anti-tumor effects by secreting high-level cytokines (such as IL-12, IL-23, IL-1 and IL-6) and chemokines (MCP-1, CCL3, CXCL9, CXCL10, etc.)." (PMID 37762054, 2023). "Current monoculture tumor spheroid models lack the presence of specific cytokines present in the PDAC TIME, such as CCL4/MIP-1β, CCL5/RANTES, CXCL9, and CXCL10 accidentally simulating an immune silent or excluded PDAC TIME." (PMID 37519820, 2023). "In the present study, we constructed cells stably expressing the three IFN-inducible chemokines CXCL9, CXCL10, and CXCL11 in a mouse model and transplanted them into nude mice to investigate their anti-tumor effects." (PMID 37218983, 2023). "Our study demonstrated another possibility that overexpression of CXCL10 and ICAM-1 in tumor cells plays a significant role to help CD8+ T cell adhesion and further activation by recognizing the alloantigens in A549 cells." (PMID 36688994, 2023). "Overall, the increased upregulation of CXCL9 and CXCL10, accompanied with the downregulation in CXCL2, may underlie the observed alterations in the cellular components at the level of systemic organs and within the tumor microenvironment following combination treatment." (PMID 36605208, 2022). "Across serum, conditioned media and both tumor types, four factors are consistently detected: CCL2, CXCL1, CXCL10 and Serpin E1." (PMID 35962398, 2022). "CXCR3 is a CXC chemokine receptor dominated by IFN-γ, which interacts with CXCL9, CXCL10, and CXCL11 to regulate tumor progression and cytokine secretion." (PMID 35571062, 2022). "Our findings demonstrate that the obese environment also leads to altered chemokine secretion in the tumor leading to a reduction of CXCL9 and CXCL10 in obese tumors." (PMID 35103755, 2022). "The cGAS-STING pathway-induced Type-1 interferon response drives the expression of multiple chemokines such as CXCL9, CXCL10, and CCL5, that act as chemical gradients to direct CTLs into the tumor tissue." (PMID 36353640, 2022). "For example, tumor CXCR3 and tumor-draining lymph node CXCL9 and CXCL10 promote the metastasis of murine melanoma cell line B16F10." (PMID 35216243, 2022). "This emphasised the key association of D14 neutrophils, PD-L1+ myeloid cells and Ly6Cintermediate monocytes with CT26 tumour size, and a more distant relationship with D7 myeloid cells, CCL17, CXCL1, CCL2, CXCL10 levels, and D14 IL-10 level." (PMID 35226704, 2022). "In the TME, M1-like macrophages are capable of recruiting and activating CD8+ T cells and NK cells via antigen presentation to the T-cell receptor and the secretion of tumor-derived chemokines including CXCL9, CXCL10, and CXCL11." (PMID 36561315, 2022). "NMU overexpression in HT29 cells induced or increased the secretion of tumour supporting cytokines (CXCL1/GROa, CXCL10/IP-10 and ICAM-1/CD54, CCL-5/RANTES, IL-8 and IL-1ra)." (PMID 36482448, 2022). "Emerging data suggests that enrichment in tumor-infiltrating CD8 + T cells and expression of immune genes such as IFN-γ, CXCL9, and CXCL10 is an indicator for immunotherapy response." (PMID 35027623, 2022).
tumor (continued). "We detected more abundant levels of sICAM-1, CXCL10, CXCL1, CCL5, TIMP-1 and TNFα in tumours treated with VV-αCEA TCE, compared to tumours treated with VV-CTRL or PBS." (PMID 36405739, 2022). "The results of necroptosis influences on the tumor immune microenvironment showed that significantly up-regulated expression levels of chemokines existed in Clusters B and C, such as CCL11, CCR1, CXCL10, and PPBP (upper part)." (PMID 35911707, 2022). "Because of the elevated levels of the tumor-secreting chemokines CCL5 and CXCL10, autophagy inhibition increases the formation of NK cells in glioblastoma in vivo." (PMID 36300110, 2022). "CXCL9, CXCL10, and CXCL11/CXCR3 are anti-tumor angiogenic factors, and the inhibition of tumor angiogenesis can be achieved via upregulating the expression of CXCL9, CXCL10, and CXCL11." (PMID 35770088, 2022). "Several chemokines (CCL2, CXCL1, CXCL2, CXCL10) were also increased in MC38 and CT26-conditioned media and tumor-bearing mouse serum." (PMID 35962398, 2022). "T-cell migration into the tumour microenvironment depends on the local production of specific chemokines, especially CXCL9 and CXCL10, which engage CXCR3 on the surface of CD8+ effector T cells." (PMID 36376335, 2022). "The expression of cytokines, such as CXCL9, CXCL10, CXCL11 and CXCL13, that attract specific immune cells at the tumor site was significantly higher in HBV and HCV tumors than in non-B, non-C tumors." (PMID 36557005, 2022). "CXCL10 promotes the proliferation of GAMS, and the elevated level of VEGFA promotes tumor angiogenesis." (PMID 36159780, 2022). "A recent immunohistochemistry and RNA-sequencing meta-analysis of resectable and advanced PDAC specimens showed a positive correlation between CCL5, CXCL9 and CXCL10 and CD8+ T cells infiltration in close proximity to tumor cells." (PMID 35954489, 2022). "As an autocrine signal, CXCL9, CXCL10, or CXCL11 activates the chemokines produced by the tumor through CXCR3A on cancer cells and further recruits immune cells to create an immune microenvironment that promotes tumors." (PMID 35992864, 2022). "Targeting CXCL10/CXCR3 signaling inhibited the mobilization of Treg and EPC, attenuated early-phase liver graft injury, and prevented late-phase tumor recurrence/metastasis after transplantation." (PMID 35634295, 2022). "The RORγt agonist increased the migration of MoDCs, which increased the local levels of CXCL10, thus promoting CD8+ T cell tumor infiltration." (PMID 35459193, 2022). "CXCL9, CXCL10, CXCL11, and CXCR3 recruited and activated immune cells, such as CD8 + T-cells, to suppress tumor progression through CXCL9,-10−11/CXCR3 axis, and they were down-regulated in the high-GATA3 group." (PMID 35647011, 2022). "Analysis of total tumor RNA extracted after 2, 4, and 7 CPA cycles revealed that the ISGs Cxcl10 and Mx1 were initially upregulated but returned to baseline after discontinuation of CPA treatment." (PMID 36187936, 2022). "Altogether, seven factors were detected both in MC38-conditioned media and MC38 tumor-bearing serum: CCL2, GDF-15, Proliferin, CXCL10, Osteopontin, PCSK9 and Serpin E1." (PMID 35962398, 2022). "Results of qRT-PCR partially demonstrated the bioinformatics results that the mRNA levels of CXCL10, CXCL9, CCL5, and CCR2 were remarkably elevated in tumor tissues collected from PTC patients coexistent with HT than those without HT (P < 0.001)." (PMID 36266640, 2022). "We also examined mRNA expression of Ccl5 and Cxcl10, two major target genes downstream of STING activation that recruit cytotoxic T lymphocytes to the tumor." (PMID 36443299, 2022). "The mRNA levels of CD169, interleukin (IL)-12, and C-X-C motif chemokine ligand 10 (CXCL10) in lymph nodes and CTL infiltration in tumors significantly increased following naringenin administration in tumor-bearing mice." (PMID 35044489, 2022).
tumor (continued). "To further explore the effect of anti-GD2 mAb plus MβCD on tumor immunity, we detected the protein expression of CD8A, caveolin-1, CXCL9, and CXCL10 by IHC staining." (PMID 36284313, 2022). "Patients that respond to PD-1 blockade also exhibited increased expression of STAT1, CXCL9, CXCL10, GZMB, CD8A, and CD8B, which is consistent with our observation in tumor model with IFNα-MSC treatment." (PMID 35145233, 2022). "In concordance with the L-R analysis, the image-based assays indicated the interacting cells mediated by CXCL10/CXCR3 and MIF/CD74 more closely co-localized with each other in tumor tissues as compared to those in NTL tissues." (PMID 35933472, 2022). "Genetic ablation of SPATA2 or CYLD in murine CRC tumors increased CXCL10 expression and T cell accumulation in the TME, concomitant with retarded tumor growth." (PMID 36531014, 2022). "CXCL10 activates and chemoattracts NK cells and CD8+ T lymphocytes to reach the site of tumors and exerts a pernicious effect on tumor cells." (PMID 36479091, 2022). "This is consistent with the detection of CXCL10 (and numerous other cytokines, chemokines and growth factors) in MC38 and CT26 cell-conditioned media, and the serum of tumor-bearing mice." (PMID 35962398, 2022). "CD8+ T cells express CXCR3 and are recruited into the tumor by the CXCR3 ligands CXCL-9, CXCL-10, CXCL-11." (PMID 36611932, 2022). "Among the INFA response-enriched genes, SAMD9, CXCL10 and CXCL11 genes overlapped in the exosomes; tumor tissue overlapped from the core enrichment genes." (PMID 36230645, 2022). "The downstream target TIL then collects chemokine genes CXCL9, CXCL10, CXCL11, and CD8 + T cell activation markers, all of which contribute to a successful anti-tumor immune response." (PMID 36071479, 2022). "Noteworthy, most cytokines with anti-tumor activity, such as IFN-γ and CXCL10, have significantly higher expression in the MRG-high subgroup." (PMID 36293001, 2022). "IL-17 was reported to inhibit T cell attracting chemokines CXCL9 and CXCL10, thereby inhibiting the recruitment of CD8+ T cells and Treg cells in CRC, which helped the immune escape of tumor cells." (PMID 35865173, 2022). "Anti-CXCR3 treatment completely abrogated the attenuated tumor growth observed in GPR182−/− mice, suggesting that the improved anti-tumor immunity seen in GPR182−/− mice is dependent on the CXCL9/CXCL10/CXCR3 axis." (PMID 35013216, 2022). "In EBV-positive NPC cells, activated NF-kB regulates a number of chemokines (CXCL9, CXCL10, CX3CL1, and CCL20), which recruit tumor-infiltrating T lymphocytes and modulate the NPC tumor environment." (PMID 36289760, 2022). "A quantitativestudy on tumor inflammation-related mRNA expression revealed inductionsof key gene expressions, such as STAT1, CXCL10, CCL5, and CCL2, andrejuvenation of TME with enhancement in T cell, macrophage, NK cell,chemokine, and cytokine functions." (PMID 36153998, 2022). "DCs were found to elevate the production of CXCL9 and CXCL10 in an IFN-γ-dependent manner, resulting in T cell infiltration to the tumor in many studies." (PMID 35459193, 2022). "Lysates of MTX-treated 9464D tumors displayed a more than 2.5-fold increase of IL1a, CXCL16, FLT3L, CX3CL1 and IL1RA, and a more than 1.5-fold increase of CXCL10, CXCL5, CCL5 and CXCL9 compared to control tumor lysates." (PMID 36397148, 2022). "In summary, we identified SPATA2 and CYLD as novel regulators of T/NK cell-attracting chemokines CXCL9, CXCL10, CXCL11 in tumor cells." (PMID 36531014, 2022). "Cxcr3 and Ccr5, the receptors for CXCL10 and CCL5, were broadly expressed on tumor-infiltrating lymphocytes, including regulatory T cells (Treg), gamma-delta (γδ) T cells, and NK cells." (PMID 36266311, 2022). "The initial findings were a reduced hepatocarcinogenesis as well as slightly reduced tumor cell proliferation and moderately enhanced tumor cell death in the DEN/CCl4-treated Cxcl10−/− mice compared to identically treated WT mice." (PMID 35897689, 2022).
tumor (continued). "The CXCL10/CXCR3 signaling pathway regulates leukocyte trafficking and angiogenesis through paracrine interactions between tumor and stromal cells." (PMID 35847936, 2022). "Here, we revealed that EGFR signaling mediates TCTP-induced resistance of tumor cells to CTL-mediated killing and decrease of T cell infiltration into the tumor by regulating MCL-1 and CXCL10." (PMID 35440620, 2022). "Inside the tumor, resident cDC1s are the primary source of CXCL9 and CXCL10 which modulate the recruitment of effector T cells." (PMID 36230990, 2022). "To depict how H89 mediates tumor recruitment of CD8+ TLs, we analyzed by RT-PCR the mRNA expression level of the chemokine CXCL10, known to attract CD8+ TLs in the TME." (PMID 35572581, 2022). "CXCL10 was a T helper 1 type chemokine and governed the trafficking of the main antitumor immune cells, including CD8+ T cells, into the tumor beds." (PMID 35259052, 2022). "Lysate from MTP-treated tumors showed an even stronger upregulation of chemokines involved in immune cell recruitment, including CXCL9, CCL5, CXCL10, CD40 and CXCL16, compared to both control and MTX-treated tumor lysates." (PMID 36397148, 2022). "Bone-homing tumor cells tend to overexpress chemokine receptors, CXCR4, CXCR6, and CXCR2 that subsequently contribute to the movement of the tumor cells from the bone marrow to other organs by seeking CXCL12, CXCL-16, and CXCL-10 respectively." (PMID 35399952, 2022). "There was a significant relationship with tumor stage in the group of CXCL2, CXCL10 and CXCL11 (P < 0.05)." (PMID 35181719, 2022). "Phosphorylated ATM was identified as a driving factor of cytokine production that can increase tumor cell-derived levels of CCL5, CXCL9, CXCL10, and IL16, leading to increased CD8+ CTL infiltration." (PMID 36071479, 2022). "IFN-γ also enhances T cell infiltration at the tumour site through the induction of chemokines (CXCL9, CXCL10 and CXCL11)." (PMID 36230780, 2022). "To analyze the TME ECM composition in more detail, we further measured the expression level of collagen 1α1 via qRT-PCR in tumor and tumor-surrounding tissue of the DEN/CCl4-treated WT and the Cxcl10−/− mice." (PMID 35897689, 2022). "Through ICD signaling, the tumor cell can produce IFN type I-II, CXCL10, HMGB1 and annexin A1 that all trigger DC maturation." (PMID 36230990, 2022). "These activated CCR6+ILC3s can secrete CXCL10 that promotes CD4+ and CD8+ T cells migration to the tumor, enhancing anti-tumor immunity and response to immune checkpoint blockade." (PMID 36341381, 2022). "We also demonstrated that increased expression of miR-15a-5p resulted in CXCL10 downregulation, followed by downregulation of the oncogene LIN28a and p-ERK signaling, leading to upregulation of the tumor suppressor let-7 family miRNAs." (PMID 34785791, 2022). "Among the chemokines known to attract CD8+ T cells into the tumor are CXCL9, CXCL10, and CXCL11, all of which bind to the chemokine receptor CXCR3 expressed at the surface of CD8+ T cells." (PMID 35439168, 2022). "DNMT1 suppresses tumor production of CXCL9 and CXCL10 and subsequently reduces T-cell tumor migration." (PMID 34385592, 2022). "For instance, EZH2, a histone 3 lysine 27 trimethylation regulator, mediates epigenetic silencing of tumor CXCL9 and CXCL10, two Th1-type chemokines, and consequently represses effector T cell trafficking into the tumor microenvironment." (PMID 35664070, 2022). "While there appeared to be significant weak-to-strong relationships among the 5 key D7 features, only CXCL10 had a significant, but weak, relationship with end-point CT26 tumour mass." (PMID 35226704, 2022). "To further investigate changes in the tumor microenvironment, we determined the levels of TAM‐produced cyto/chemokines Ccl2, Ifnγ, Cxcl10, Cxcl9, Csf1, Csf3, and Il‐6 in the peritoneal lavage." (PMID 36221913, 2022).
tumor (continued). "It seems that promoted numbers of CTLs in tumor tissue, as evidenced in previous study, rely on the improved expression of T cell-attracting chemokines (CXCL9, CXCL10, and CCL5) as shown in colon cancer MC38 cell bearing mice upon oxaliplatin treatment." (PMID 34980128, 2022). "Neutralizing CXCL9, CXCL10, or IFN-γ reduces CXCR3-expressing activated T cells infiltrating tumors and abrogates IL-7/IL-7rα-Fc-mediated tumor growth inhibition." (PMID 36479091, 2022). "By releasing an extracellular regulator, galectin-3, tumor cells are capable of blocking interferon gamma (IFN-γ) in the TME followed by impeding chemokines CXCL9, CXCL10, and CXCL11 leading to obstructed T-cell recruitment into the tumor bed." (PMID 35053449, 2022). "CXCL9, CXCL10, and CXCL11/CXCR3 axes can induce immune activation and then inhibit tumor growth, which are potential novel therapeutic targets for cancer therapy." (PMID 36090326, 2022). "More specifically, we have detected increased levels of sICAM-1, CXCL10, CXCL1, CCL5, TIMP-1 and TNFα in tumours treated with VV-αCEA TCE, compared to tumours treated with VV-CTRL or PBS." (PMID 36405739, 2022). "ELISA analysis of tumour lysates validated the increasedexpression of T-cell chemoattractants (CXCL9 and CXCL10) uponKRASG12C inhibition." (PMID 35930804, 2022). "Subsequently, the up-regulation of CCL5, CXCL10, and IFN-γ in LLC tumor tissues was confirmed by real-time PCR." (PMID 35002511, 2022). "The expression levels of other hub genes CTLA4, CXCL10, CCL5, CCl4, ICAM1, CXCL9, CD27, GZMB, FCGR2A, SELL, IDO1 in SKCM were higher than those in non-tumor skin tissues (P < 0.05), and the results were statistically significant." (PMID 35710862, 2022). "Compared with the level of CXCL10 in BAL fluid, the expression of CXLC10 by persistent tumor cells was significantly decreased immediately after 1 day of erlotinib treatment, but it gradually increased with erlotinib treatment." (PMID 36612121, 2022). "CXCL9, CXCL10, and CXCL11 bind to CXCR3 and regulate lymphocyte chemotaxis to mediate recruitment of tumor-infiltrating lymphocytes (TIL) for tumor-suppressor activity." (PMID 35269786, 2022). "IFN-γ promotes the infiltration of the tumor with leukocytes, including CD8 T cells, by driving the secretion of CXCL9 and CXCL10." (PMID 35103755, 2022). "Results of qRT-PCR partially demonstrated the bioinformatics results that the mRNA levels of CXCL10, CXCL9, CCL5, and CCR2 were remarkably elevated in tumor tissues collected from PTC patients coexistent with HT than those without HT." (PMID 36266640, 2022). "Fourth, despite the impressive promotion in tumor immunity, the roles of the four chemokines-CXCL9, CXCL10, CXCL11, and CCL5-in tumorigenesis and progression were still in debates." (PMID 35692828, 2022). "The chemokine CXC motif receptor 3 (CXCR3), the CXCL9, CXCL10 and CXCL11 specific receptor, participates in the tumor migration, invasion, angiogenesis and immunity and are mainly expressed on monocytes, effector T cells, NK lymphocytes and cancer cells." (PMID 36030223, 2022). "Taken together, these data are suggestive of defective tumour immune surveillance in CDH17 ‘high’ versus ‘low methylation’ status stage II CC tumours, despite evidence by RNAseq of expression of IFN-γ and CXCL10 (top gene in the IFN beta signature, by GSEA)." (PMID 36612154, 2022). "We next compared the circulating levels of CXCL1, CXCL10 and CXCL13 between BTC patients with different tumor and clinical characteristics." (PMID 36077611, 2022). "Compounds that enhance the expression of CXCL9, CXCL10 or CXCL11 and decrease the expression of CXCR3 on tumor cells have displayed anti-tumor activity." (PMID 35154121, 2022). "Calculation of the area fraction demonstrated an overall upregulated level of αSMA as well as COLIV in tumor and tumor-surrounding tissue of the DEN/CCl4-treated Cxcl10−/− mice compared to their WT counterparts." (PMID 35897689, 2022).